DRD1 (dopamine receptor D1)
Diseases named in the same sentence as DRD1 in open-access papers (continued):
Sharing a sentence is not in itself a finding about the gene and the disease.
cerebral palsy (1 paper, 2018). A group of disorders affecting the development of movement and posture, often accompanied by disturbances of sensation, perception, cognition, and behavior. "The results indicated that there was a statistically significant association between a polygenic dopamine gene score reflecting the collective effects of five dopamine gene polymorphisms (COMT, DAT, DRD1, DRD2, and DRD3), and CIMT outcome in 33 children with spastic unilateral cerebral palsy." (PMID 29339100, 2018).
cholangiocarcinoma (1 paper, 2024). A carcinoma that arises from the intrahepatic biliary tree (intrahepatic cholangiocarcinoma) or from the junction, or adjacent to the junction, of the right and left hepatic ducts (hilar cholangiocarcinoma). "Drugs that inhibit DRD1 feedback signals combined with conventional chemotherapy may be a novel therapy for cholangiocarcinoma." (PMID 38494840, 2024). "In cholangiocarcinoma (BDC), DRD1 acts as a key protein involved in the proliferation of autonomous cancer stem cell‐like cells (CSCs) by regulating endogenous Wnt Family Member 7B (WNT7B)." (PMID 38494840, 2024).
dwarfism (1 paper, 2019). "Variants associated with OSD have been identified in COL9A3 in the Labrador Retriever and in COL9A2 in the Samoyed dog, termed drd1 and drd2 (dwarfism with retinal dysplasia 1 and 2) respectively." (PMID 31415586, 2019). "Autosomal recessive OSD caused by COL9A3 and COL9A2 mutations have previously been identified in the Labrador Retriever (dwarfism with retinal dysplasia 1—drd1) and Samoyed dog (dwarfism with retinal dysplasia 2—drd2) respectively; both of those mutations were excluded in all affected NID." (PMID 31415586, 2019).
edema (1 paper, 2021). An abnormal accumulation of fluid beneath the skin, or in one or more cavities of the body. "The protective effect of a specific DRD1 agonist resulted in a reduction of endothelial dysfunction, thus attenuating leukocyte infiltration and pulmonary edema induced following mechanical stretch." (PMID 33456556, 2021).
endothelial dysfunction (1 paper, 2021). In vascular diseases, endothelial dysfunction is a systemic pathological state of the endothelium (the inner lining of blood vessels) and can be broadly defined as an imbalance between vasodilating and vasoconstricting substances produced by (or acting on) the endothelium. "Notably, the present study showed that dopamine protected against mechanical stretch-induced endothelial dysfunction via DRD1/cAMP signaling pathway." (PMID 33456556, 2021). "Whether AMPK signaling pathway is involved in DRD1-mediated protection against mechanical stretch-induced endothelial dysfunction through mutual regulation with HDAC6 merits further investigation." (PMID 33456556, 2021).
Euphoria (1 paper, 2013). Elevation of emotional tone or mood that significantly deviates from normative affective functioning. "In conclusion, DRD1 rs686 minor allele decreases OD risk by slowing down the transition to dependence and attenuating opioid-induced euphoria." (PMID 23976958, 2013). "An analysis stratified by efficiency of transition to dependence and subjective response, gender, AOO, and type of initial OD revealed a significant association between DRD1 and OD with fast transition (DTFUD≤30 days), OD with first comfortable response, as well as OD with post-dependence euphoria." (PMID 23976958, 2013).
gastric cancer (1 paper, 2023). A primary or metastatic malignant neoplasm involving the stomach. "Thus, the NLRP3 inflammasome promotes gastric cancer and its downregulation by the activity of the aryl hydrocarbon receptor (AhR), dopamine receptor D1 (DRD1) and G protein-coupled bile acid receptor 1, (GPBAR1) may limit the occurrence of pyroptosis, thereby affecting cancer progression." (PMID 37081882, 2023).
Hallucinations (1 paper, 2017). Perceptions in a conscious and awake state that, in the absence of external stimuli, have qualities of real perception. "Work from our group showed that the TT genotype at DRD1 rs686 may predispose PD patients to developing visual hallucinations (VHs) while subjects with GG at DRD1 rs4532 display a shorter time to VHs." (PMID 28125015, 2017).
inflammatory bowel disease (1 paper, 2021). A spectrum of small and large bowel inflammatory diseases of unknown etiology. "In recent years, both DRD1 and DRD2 agonists have been shown to prevent the development of vascular hyperpermeability in animal models of ALI 40, 42, ovarian hyperstimulation syndrome 48, and inflammatory bowel disease." (PMID 33456556, 2021).
injury (1 paper, 2021). Damage inflicted on the body as the direct or indirect result of an external force, with or without disruption of structural continuity. "We then examined the effect of mechanical stretch on the pulmonary levels of DRD1, DRD2, TH and DDC in a murine model of mechanical ventilation-induced lung injury." (PMID 33456556, 2021).
Insulin resistance (1 paper, 2023). Increased resistance towards insulin, that is, diminished effectiveness of insulin in reducing blood glucose levels. "Such moderate positive correlations are maintained and increased only in patients with insulin resistance in relation to DRD1 (r = 0.386, p = 0.0008) and DRD4 (r = 0.419, p = 0.0003), being absent in insulin-sensitive patients." (PMID 36768789, 2023). "Nevertheless, we found moderate positive correlations between DRD1/DRD4 and GLP1R, especially in patients with insulin resistance, suggesting that GLP1R expression is associated with the decreased expression of dopamine receptors in patients with insulin resistance." (PMID 36768789, 2023).
intracerebral hemorrhage (1 paper, 2018). A cerebrovascular disorder characterized by bleeding into one or both cerebral hemispheres including the basal ganglia and the cerebral cortex. "The present study aims to investigate the role of DRD1 on neuroinflammation in intracerebral hemorrhage (ICH) mice and the potential mechanism mediated by NLRP3 inhibition." (PMID 29301581, 2018).
kidney damage (1 paper, 2012). "Also, microalbuminuria was almost 10 times higher in these patients as compared to the G/G homozygous, indicating a larger kidney damage associated to the hypertensive state depending upon the DRD1 genotype." (PMID 23905040, 2012).
lung adenocarcinoma (1 paper, 2024). A carcinoma that arises from the lung and is characterized by the presence of malignant glandular epithelial cells. "Interestingly, we also found that decreased DRD1 expression coupled with increased methylation of its promoter is observed across several tumor types and that high DRD1 expression is associated with better prognosis in stage I lung adenocarcinoma." (PMID 38572507, 2024). "Thus, DRD1 levels may be most relevant for early‐stage lung adenocarcinoma, and notably, our analysis of the NCI‐MD study patients focused on stage I LUAD." (PMID 38572507, 2024).
mental disorder (1 paper, 2018). A disease that has its basis in the disruption of mental process. "In our results, therapeutic targets or biomarkers of neurological disorder and mental disorder, such as DRD1, DRD2, DRD4, HTR2A, PRL and ADRA2A, were assigned with high scores in both mirtazapine and pramipexole." (PMID 29371651, 2018).
psoriasis (1 paper, 2022). An autoimmune condition characterized by red, well-delineated plaques with silvery scales that are usually on the extensor surfaces and scalp. "Fenoldopam mesylate, 6-chloro-2, 3, 4, 5-tetrahydro-l- (4- hydroxyphenyl)–1H-3-benzazepine-7, 8-diol, methane sulfonate (FD, a highly selective DRD1 agonist) therapeutic efficacy in psoriasis has been suggested by several researchers." (PMID 36662067, 2022).
psychostimulant addiction (1 paper, 2021). "Moreover, shRNA-induced Gadd45b knockdown decreases expression of genes involved in psychostimulant addiction, blocks induction of immediate early genes by DRD1 stimulation, and prevents DRD1-mediated changes in DNA methylation." (PMID 32927466, 2021).
Retinal dysplasia (1 paper, 2022). Abnormal growth and differentiation, structure and appearance of the retina present from birth. "It would be of interest to examine whether canine SLC4A5 or other known regulators of RPE fluid flow are altered in drd1 and drd2 canines exhibiting retinal dysplasia." (PMID 35216333, 2022).
uveitis (1 paper, 2021). An inflammatory process affecting a part of or the entire uvea. "The importance of the dopaminergic system has also been shown in endotoxin-induced uveitis, in which a mixed DRD2 agonist/DRD1 antagonist was able to reduce immune-cell infiltrates in the eye." (PMID 35008877, 2021).
Ventriculomegaly (1 paper, 2025). An increase in size of the ventricular system of the brain. "In progressive ventriculomegaly models, reduced expression of Drd1-targeting microRNAs, particularly miR-674-3p, led to elevated dopamine receptor Drd1 levels, contributing to ciliary motility defects." (PMID 40422900, 2025).
vitiligo (1 paper, 2021). Generalized well circumscribed patches of leukoderma that are generally distributed over symmetric body locations and is due to autoimmune destruction of melanocytes. "The expression of DA and DRD1 seems to be increased in vitiligo patients, as DA seems to act in the direction of promoting apoptosis of melanocytes and inhibiting melanogenesis." (PMID 34360837, 2021). "DRD1 levels are decreased in blood sera of vitiligo patients compared with controls." (PMID 34360837, 2021). "Therefore, inhibiting the action of DA or blocking the activation of DRD1 in vitiligo patients may promote melanogenesis." (PMID 34360837, 2021). "The mRNA expression of DRD1 and DRD5, including GPX1, dopa decarboxylase (DDC), and monoamine oxidase A (MAOA), differs in vitiliginous skin, and the protein levels of DRD1, DRD5, DDC, MAOA, and MAOB vary in the skin and/or blood serum of patients with vitiligo." (PMID 34360837, 2021).
tumor (25 papers, 2017 to 2025). "The effects of dopamine receptors on cell proliferation have been reviewed extensively and generally appear to be tissue‐type dependent but with a growing number of tumor types associated with DRD1 as a tumor suppressor." (PMID 38572507, 2024). "Another study demonstrated the overexpression of DRD1 mRNA in a broad spectrum of common and rare cancers, and various signalling pathways were closely associated with tumour initiation and tumour progression." (PMID 34717619, 2021). "Bioluminescence imaging demonstrated that loss of DRD1 suppressed tumor growth in vivo." (PMID 38246990, 2024). "Our results add a new facet to current knowledge on tumor neural interactions, highlighting DRD1 as a target within the GBM invasive compartment." (PMID 38246990, 2024). "We show that SKF83566 suppress GBM progression and invasion via the DRD1-c-Myc-UHRF1 axis in vitro as well as in an orthotopic tumor model in mice." (PMID 38246990, 2024). "BG5-sh-DRD1 tumors had reduced bioluminescence intensity (that represents a proxy for tumor volume) and were less invasive relative to controls." (PMID 38246990, 2024). "More complex in vitro co‐culture systems and in vivo syngeneic models are required to make further conclusions about the effects of DRD1 on the tumor microenvironment and on the functions of immune effector cells." (PMID 38572507, 2024). "Contrary to the controversial role of DRD1 in promoting tumor growth but also inhibiting immunosuppression, DRD1 agonists were proven to exert a major anti-tumor effect in several preclinical models." (PMID 37215113, 2023). "In the regulatory mechanism, loading-driven dopamine exerts its tumor-suppressing effect via DRD1, while the effects of FP are mediated via DRD2." (PMID 34031366, 2021). "Loading-driven dopamine downregulated Lrp5 in 4T1Br brain-metastasized tumor cells via dopamine receptor D1, followed by a reduction in CCN4, an oncogene inducible by Wnt signaling." (PMID 34031366, 2021). "Aberrant DRD1 expression has been validated to correlate with various tumours and to be involved in tumour cell migration, tissue inflammation, autophagy activation, tumour growth, tumour progression and cancer cell biology." (PMID 34717619, 2021). "The PCR results of eight pairs of tumour tissues and adjacent normal tissues indicated that DRD1 expression was decreased in HCC tissues (p = 0.0337)." (PMID 34717619, 2021). "To determine the tumor-suppressing mechanism induced by loading-driven dopamine increases, we focused on two dopamine receptors, DRD1 and DRD2, as representatives of types D1 and D2, respectively." (PMID 34031366, 2021). "In this study, we determined that DRD1 expression was decreased in HCC tumour tissues versus normal tissues and that low DRD1 expression indicated a poor prognosis." (PMID 34717619, 2021). "It was consistent that oncogenic miR-21 and miR-155 involved in the progression and invasion of GBM, and a set of their common key targets such as LHX6, DRD1, NEUROG1 and RAB27B were also associated with tumor progression." (PMID 29312626, 2017). "SCH23390 is a selective DRD1 antagonist that exerts tumour‐inhibiting effects in vitro and in vivo." (PMID 38494840, 2024). "As the promoter of DRD1 lies in a CpG island, we assessed whether the downregulation of DRD1 corresponds with increased methylation of the DRD1 promoter in tumor versus normal tissue." (PMID 38572507, 2024). "However, the upregulation of DRD1 agitates tumor growth and meanwhile inhibits immunosuppression, but displays an anti-tumor effect in preclinical models." (PMID 37215113, 2023). "Breast cancer and HCC patients positive for DRD1 expression have a poor prognosis, and dopamine receptor inhibitors can destroy tumor cells by terminating the self-renewal of tumor stem cells; moreover, they can also inhibit AKT signaling pathways, leading to suppression of breast tumor growth." (PMID 36456906, 2022).
tumor (continued). "After analyzing any correlations between MYCN and DRD1 expressions and tumor immune-cell types, we found that the high expression of DRD1 in CA was positively correlated with immune activation, and that the high expression of MYCN in CB was positively correlated with immunosuppression." (PMID 34212175, 2021). "The significance of DRD1 expression varied among different tumour samples." (PMID 34717619, 2021). "Furthermore, we uncovered markedly mitigated DRD1 expression in advanced stages and tumour grades compared with early stages and grades of HCC." (PMID 34717619, 2021). "Expression of DRD1 on endothelial cells varied per tumour type." (PMID 31478179, 2020). "Importantly, previous researches have reported the dopamine could impact inflammasome through DRD148, we then hypothesized that the decreased expression of DRD1 might impact the inflammasome microenvironment of MES-like high tumor." (PMID 36720864, 2023). "Notably, dopamine downregulated Lrp5 via DRD1 in tumor cells." (PMID 34031366, 2021). "DA influences tumor behavior via its receptors, categorized as D1-like (DRD1, DRD5) and D2-like (DRD2, DRD3, DRD4), which vary in tumor expression and function." (PMID 40456735, 2025). "DRD1 is expressed in normal lung respiratory epithelial cells, and its expression is reduced in NSCLC tumor tissues at least partially through promoter methylation." (PMID 38572507, 2024). "Kaplan-Meier analysis furthermore showed that BG5-sh-DRD1 tumor-bearing mice exhibited longer survival (142 days vs. 159 days, BG5-sh-NC vs. BG5-sh-DRD1 tumors)." (PMID 38246990, 2024). "To more directly interrogate the role of DRD1 in mediating patient response to ICI, we queried the Tumor Immune Dysfunction and Exclusion (TIDE) database to harness gene expression data from clinical trials of checkpoint inhibitors." (PMID 38572507, 2024). "The direct effect of dopamine on tumour cells is supported by studies in which dopaminergic drugs targeting DRD1 and DRD2 exert therapeutic effects in preclinical cancer models by inhibiting tumour proliferation and inducing death of tumour cells." (PMID 36428964, 2022). "For instance, Wu and colleagues have shown that the pharmacologic stimulation of type I dopamine receptors (including DRD1 and DRD5) reduces the suppressive function of MDSC, thus enhancing the potency of the T-cell-mediated anti-tumour response." (PMID 36428964, 2022). "We further show that SKF83566 inhibits tumor cell invasion and malignant progression by specifically targeting DRD1 but not DRD5." (PMID 38246990, 2024). "However, there are little research related to the effect of DRD3 in HCC cancer progression, while numerous studies about the carcinogenesis of DRD1 and DRD2 have been published, and tumor-related research on DRD3 is rare." (PMID 36456906, 2022). "Interestingly, DRD1 expression showed obvious differences between patients with different TNM stages and tumour grades." (PMID 34717619, 2021). "Therefore, we deeply explored DRD1 expression, which was remarkably decreased in HCC primary tumour tissues compared with normal tissues." (PMID 34717619, 2021). "Therefore, we screened a large tumour set for receptor mRNA overexpression using functional genomic mRNA (FGmRNA) profiling, and we analysed protein expression and location of 5-HTR1B, 5-HTR2B, DRD1, and DRD2 with immunohistochemistry in different tumour types." (PMID 31478179, 2020).